HNRNPA1 (heterogeneous nuclear ribonucleoprotein A1)
Diseases named in the same sentence as HNRNPA1 in open-access papers (continued):
Sharing a sentence is not in itself a finding about the gene and the disease.
cancer (continued). "It is worth noting that hnRNPA1 has been shown to alter aerobic glycolysis of cancer cells by directing the alternative splicing of pyruvate kinase (PKM)." (PMID 35879279, 2022). "A large body of evidence suggests that hnRNPA/B, especially hnRNPA1 and A2/B1, have a good clinical value as a marker for early cancer diagnosis, disease monitoring, prognosis assessment and efficacy evaluation." (PMID 35879279, 2022). "Presently, many existing drugs, foods and plant ingredients have been unearthed in succession for cancer treatment by targeting hnRNPA1." (PMID 35879279, 2022). "In PCa, hnRNPA1 was identified as a direct anti-cancer target of quercetin, a flavonoid abundantly present in plants." (PMID 35879279, 2022). "As the research on hnRNPA1 moves along, its application in cancers will attract more and more attention." (PMID 35879279, 2022). "With the deepening of clinical and basic research on hnRNPA1, its important role in cancer origination and progression continues to emerge." (PMID 35879279, 2022). "In recognition of the importance of hnRNPA1, numerous hnRNPA1-targeting compounds have been developed successively for clinical treatment of cancers." (PMID 35879279, 2022). "The ectopic expression of hnRNPA1 at different disease stages or sites has been progressively proved to be correlated with pathophysiological features and clinical prognosis of cancers, indicating hnRNPA1 as a promising cancer biomarker." (PMID 35879279, 2022). "Taken together, PRMT4, PRMT5, PRMT7 and potentially hnRNPA1 arginine methylation were required for the growth of multiple types of cancer cells." (PMID 33782401, 2021). "The STAT3/hnRNPA1 pathway can partially explain the up‐regulation of miR‐27b‐3p in EMT cancer cell‐derived exosomes." (PMID 34936736, 2021). "Arginine methylation in the RGG domain of hnRNPA1 was often significantly higher than that in normal samples in all three types of cancers." (PMID 33782401, 2021). "We also checked the effects of USP7 and hnRNPA1 on biological behavior of cancer cells, both USP7 and hnRNPA1 showed a positive link with increased cell viability, but had only slight influence on cell cycle." (PMID 34845198, 2021). "Altogether, the cancer-specific isoform switch we describe here for HNRNPA1 emphasizes the need to study gene expression at the isoform level in cancers to identify novel cases of oncogene activation." (PMID 34961772, 2021). "Heterogeneous nuclear ribonucleoprotein A1 (hnRNPA1) is a ubiquitous RNA splicing factor that is overexpressed and prognostically relevant in various human cancer types." (PMID 32417965, 2020). "In contrast, the cancer genes HNRNPA1, PPP2RC5, STRAP, DNAJC14, ATF1 showed upregulation in the cell subpopulations GSC and CD133pos./CD15pos. cells and are located in chromosomal regions that had gains in GSC and CD133pos./CD15pos. cells." (PMID 32634135, 2020). "The cancer genes HNRNPA1, PPP2RC5, STRAP, DNAJC14, and ATF1 showed upregulation in GSC and CD133pos./CD15pos. cells and were included in chromosomal regions that showed gains for GSCs and CD133pos./CD15pos.cells." (PMID 32634135, 2020). "The results of previous studies and our analysis all suggested the critical role of HNRNPA1 in the initiation and development of different types of cancers." (PMID 32915499, 2020). "Heterogeneous distributions of hnRNP genes were observed in different cancer types: HNRNPA1 and HNRNPAB were highly expressed in most tumours." (PMID 32915499, 2020). "HnRNP genes demonstrated heterogeneous distributions in different cancer types: HNRNPA1 and HNRNPAB were highly expressed in most tumours; HNRNPA1P33 expression was increased in COAD, READ and LUAD whereas decreased in CHOL, PRAD and BLCA." (PMID 32915499, 2020). "For example, quercetin can inhibit the expression of heterogeneous nuclear ribonucleoprotein A1 (hnRNPA1), which controls mRNA exports of anti-apoptotic genes, thereby enhancing other anti-cancer agents, such as enzalutamide and JQ1." (PMID 33066509, 2020).
cancer (continued). "hnRNPA1 immunostaining was interpretable in 14,258 cancers and considered strong in 33.4%, moderate in 45.9%, weak in 15.3%, and negative in 5.4%." (PMID 32417965, 2020). "A search for associations between hnRNPA1 and deletions must, therefore, be restricted to subgroups of ERG-positive and ERG-negative cancers." (PMID 32417965, 2020). "It was recently shown that hnRNPA1 regulates the stability of G-quadruplex (G4) structures in certain promoters and regulates the expression of cancer-related genes, such as KRAS35,36." (PMID 31311954, 2019). "The heterogeneous nuclear ribonucleoprotein A1 (hnRNP A1) is a versatile RNA-binding protein playing a critical role in alternative pre-mRNA splicing regulation in cancer." (PMID 30791548, 2019). "Expression of SRSF1, SRSF2, SRSF3, SRSF5, SRSF6, hnRNPA1, hnRNPA2, hnRNPB1, hnRNPH, and hnRNPK is frequently disturbed in cancers, which leads to impaired alternative splicing of key apoptotic mRNA targets." (PMID 29495341, 2018). "This was found to lead to the suppression of heterogeneous nuclear ribonucleoprotein A1 (HNRNPA1), which is up-regulated in a wide variety of cancers, and to the inhibition of cell proliferation." (PMID 29872500, 2018). "Taken together, these data suggested that the axis of resveratrol and resveratrol-regulated miRNAs functionally control the expression of HNRNPA1, which is involved in cancer cell proliferation." (PMID 29872500, 2018). "In cancer or embryonic cells, increased hnRNPA1/2 proteins by c-Myc or others promotes exon 10 splicing and inclusion resulting in generation of pyruvate kinase isozyme type M2 (PKM2)." (PMID 28086949, 2017). "It is known that NEK2 is a potential target of c-Myc from chromatin immunoprecipitation (ChIP) sequencing, and c-Myc regulates pyruvate kinase mRNA splicing in cancer by upregulation of hnRNPA1/2 and PBT." (PMID 28086949, 2017). "In paired sample (cancer/NM from each same patient) comparison of stomach samples, only HNRNPA1 showed >50 % upregulation (cancer/NM >2) incidence (UI), followed by the other UIs in the order of HNRNPA1 (52 %), SRSF7 (42 %), and other SF proteins (22 %–33 %)." (PMID 27282379, 2016). "Currently, no reports have shown, with statistical significance, elevated levels of SRSF7 in any type of primary cancer or elevated levels of HNRNPA1 in primary GC samples." (PMID 27282379, 2016). "In contrast, in this study, HNRNPA1 protein levels presented remarkably elevated levels (>4.4-fold) in both cancers." (PMID 27282379, 2016). "This showed 2.9-fold up-regulation of CBX5 relative to hnRNPA1 in MCF7 cells versus non-cancer breast epithelial cells (HMEC) and 0.62-fold down-regulation in MDA-MB-231 cells relative to HMEC." (PMID 26791953, 2016). "Considering the UIs and DAs among the six SFs, HNRNPA1 was the most effective marker for both cancers." (PMID 27282379, 2016). "Of the SFs, only HNRNPA1 presented greater than 50 % upregulation (cancer/normal mucosa > 2-fold) incidences and CEA-comparable, acceptable (>70 %) detection accuracy (74 %) for GC." (PMID 27282379, 2016). "Expression levels for HP1α-V3, STET, and hnRNPA1 mRNA were measured by RT-qPCR in the normal breast, primary carcinoma samples and lymph node metastases." (PMID 26791953, 2016). "mTOR activation mediated by MHY1485 was able to restore the expression of c-Myc, hnRNPA1, and hnRNPA2 in OA-treated cancer cells." (PMID 24626155, 2014). "In cancer, several oncogenes and tumour promoters are translationally controlled by hnRNPA1, including cMYC, Cyclin D1, FGF-2, XIAP and BCL-XL (this report), all of which possess IRESs in their mRNAs." (PMID 25324306, 2014). "A critical functional consequence for observations connecting HNRNPA1 upregulation with cell proliferation, transformation has been demonstrated in a wide variety of cancers." (PMID 21645413, 2011). "Numerous miRNA inhibitors have been discovered targeting HNRNPA1 in various cancers." (PMID 39062595, 2024).
cancer (continued). "Specifically, the mRNA expression level of hnRNPA1 was increased in the HCC cell (SMMC 7721 and Hep G2) compared with normal liver cells (L02 and LX-2), also the mRNA expression level of hnRNPA1 was increased in other cancer cells (U251, Hela and B16-F10) (p < 0.001)." (PMID 39834948, 2024). "The functional group of RNA binding proteins included ELAVL1, ZRANB2 and HNRNPA1, whose role in alternative splicing of transcripts to serve tumour development have made them a focus of recent efforts to target altered RNA splicing in cancer." (PMID 37997254, 2024). "By targeting this interaction, PRMT5 inhibitors could effectively impair HNRNPA1’s tumor-promoting activities, thereby curbing cancer progression and offering new avenues for cancer treatment." (PMID 39341825, 2024). "Moreover, another plant-derived oleanolic acid induces a transition from PKM2 to PKM1 by inhibiting mTOR signaling and the c-Myc-dependent expressions of hnRNPA1 and hnRNPA2, thus weakening the glycolytic ability of cancer cells." (PMID 38785973, 2024). "Certainly, hnRNPA1 was also a critical mediator for multiple cancer regulators." (PMID 35879279, 2022). "Given its significance in cancer, hnRNPA1 has also been employed as a drug target in clinical trials, which may bring a new opportunity for cancer prevention and treatment in the near future." (PMID 35879279, 2022). "HnRNPA1 is a biomarker with considerable clinical transformation value, whether for cancer early screening or targeted therapy." (PMID 35879279, 2022). "Collectively, the molecular mechanisms of hnRNPA1 in cancer development are complicated, whether it is involved in pre-mRNA splicing and processing, competitively binding to varied RNAs, or assisting in EVs packaging and secretion." (PMID 35879279, 2022). "Additionally, it has been reported that hnRNPA1 participates in the sorting of RNAs into EVs to affect the various biological features of cancer." (PMID 35579947, 2022). "HnRNPA1 is the most well studied member of hnRNPA/B and plays a key role in a variety of cancers." (PMID 35879279, 2022). "Detailedly, hnRNPA1 encapsulated miR-27b-3p into exosomes and delivered them into vascular endothelial cells, setting the stage for subsequent exosomal miR-27b-3p promotion of circulating tumor cell-mediated cancer cell metastasis." (PMID 35879279, 2022). "Moreover, mRNA amplification and DNA methylation levels of hnRNPA1 were increased in tumor tissues, indicating that hnRNPA1 overexpression was closely related to the progression of cancers." (PMID 35875075, 2022). "Further drug optimization and biological validation could offer opportunities to develop cancer treatments with hnRNPA1 inhibitors." (PMID 34065983, 2021). "Finally, the family members hnRNPA1, hnRNPA2 and hnRNPI were shown to regulate the typical metabolic switch in cancer cells from oxidative phosphorylation to aerobic glycolysis known as the Warburg effect." (PMID 34065983, 2021). "We further demonstrated that lncRNA SCIRT was also increased in cancer cell exosomes and may facilitate the exosomal loading of miR-665 with the help of hnRNPA1." (PMID 34349799, 2021). "In the event where hnRNPA1 is downregulated, cancer-specific apoptosis is induced." (PMID 33498485, 2021). "Given that hnRNPA1 was strongly associated with ERG-positive cancers itself, it was expected that hnRNPA1 was positively linked to all ERG-associated deletions and inversely linked to all deletions associated to ERG-negative cancers." (PMID 32417965, 2020).
cancer (continued). "In addition, HNRNPA1 predicted worse prognosis of cancers including ACC, KIRP, LUAD and PAAD but was associated with better survival in cancers of KIRC, LGG, THYM and UCEC." (PMID 32915499, 2020). "It was, thus, not surprising that the ERG-associated hnRNPA1 was linked positively to ERG-associated deletions but inversely to those deletions that prevail in ERG-negative cancers." (PMID 32417965, 2020). "This developmental splicing activity agrees with prior studies that have shown that HNRNPA1 is highly expressed in proliferating cells and a wide range of cancers, but is either undetectable or present at much lower levels in most normal differentiated tissues." (PMID 32086392, 2020). "Data on hnRNPA1 and AR expression were available from 7157 cancers." (PMID 32417965, 2020). "As hnRNPA1 contributes to the progression of multiple cancers, we further explored whether hnRNPA1 acted as an oncogene in PDAC." (PMID 32085715, 2020). "hnRNPA1 was expressed in normal prostate glandular cells but often overexpressed in cancer cells." (PMID 32417965, 2020). "For instance, HNRNPA1 and HNRNPC showed different prognostic association in diverse cancer types, which were therefore shown by forest plot to illustrate the specific predictive effect in diverse types of cancers." (PMID 32915499, 2020). "Alternative splicing of cancer-associated genes such as fibroblast growth factor and insulin receptors, signaling kinases such as SRC and RAS, or the BRCA1 tumor suppressor have been reported from hnRNPA1-deregulated cells." (PMID 32417965, 2020). "From the gene-interaction network analysis, we found that the genes with survival-associated AS events including HNRNPA1, RPS5, DDX55, and OFD1 were hub nodes of the network which might play vital roles in cancer progress." (PMID 32595697, 2020). "Moreover, they report that differential splicing of HNRNPA1 - whose expression levels are altered in several cancer types - leads to transcript degradation." (PMID 32204435, 2020). "hnRNPA1, which is overexpressed in a number of cancers, contributes to tumor progression." (PMID 31480735, 2019). "Down-regulation of HNRNPA1 could suppress tumorigenesis by cell cycle arrest or by inducing apoptosis in cancer cells." (PMID 31257225, 2019). "Moreover, hnRNPA1 knockdown enhanced the effects of JQ1 at suppressing sphere-forming ability of cancer cells." (PMID 31480735, 2019). "Considering these results, TRA2B gene transcripts and hnRNPA1 or hnRNPU may be closely interacting regulators of the cell cycle or cell growth, which is a crucial phonotype of cancer cells." (PMID 31311954, 2019). "Altogether, these results suggested that down-regulation of HN1 and HNRNPA1 could inhibit cancer-related cell phenotypes and contribute to patient survival." (PMID 31257225, 2019). "It will be of interest to examine whether resveratrol can regulate its target miRNAs (miR-34a, miR-424, and miR-503) and HNRNPA1 expression in other types of cancer." (PMID 29872500, 2018). "In this research, we investigated whether and how estradiol correlate to cancer cell behaviors through heterogeneous nuclear ribonucleoprotein (hnRNPA1) and MDM2." (PMID 28035066, 2017). "The FIR-SAP155 (SF3B1) interaction affects both hnRNPA1 and c-Myc expression and may represent a therapeutic target in c-Myc-driven cancer." (PMID 28978087, 2017). "With future demand for clinical applications of SK-induced ICD in tumor cells for development of cancer vaccines, next we explored the pharmacological mechanisms by which SK may target the human hnRNPA1/SK complex." (PMID 27248319, 2016). "Indeed increased expression of HNRNPA1 has been observed to correlate with decreased HNRNPA2/B1 in some cancer cell lines." (PMID 20946641, 2010).
cancer (continued). "Therefore, the function of hnRNPA1 appears to be a double-edged sword, which not only reflects the dynamic heterogeneity of malignant tumors but also broadens our knowledge and understanding of the regulatory mechanism of hnRNPA1 in tumor occurrence and metastasis." (PMID 38268030, 2024). "As in other cancers, hnRNPA1-mediated variable splicing of PKM was essential for accelerating cellular glycolysis, and upstream promoters such as lncRNA SNHG6 and ESCO2, and repressors such as RBMX and miR-206 may affect the smooth advancement of this process by interacting with hnRNPA1." (PMID 35879279, 2022). "Binding to the C-terminal region of hnRNPA1, quercetin hindered hnRNPA1’s combination with transportin 1 (Tnpo1), leading to its cytoplasmic retention and subsequent recruitment of hnRNPA1 to stress granules (SGs), ultimately putting cancer cells on the path to apoptosis." (PMID 35879279, 2022). "Therefore, based on existing research, hnRNPA1 was identified as a novel cancer indicator." (PMID 35879279, 2022). "Interestingly, these miRNAs were enriched for their predicted and confirmed mRNA targets in cancer-related pathways and signaling cascades which may partly explain the phenotypic changes we detected in HNRNPA1 silenced cancer cells." (PMID 34961772, 2021). "This shows that quercetin enhances the effects of BET inhibitor JQ1 by inhibiting expression of the hnRNPA1 gene, and combined administration may have promising application prospects for cancer patients, especially regarding patients with thyroid and pancreatic cancer." (PMID 34235089, 2021). "Importantly, our data also revealed that lncRNA SCIRT and the hnRNPA1 protein might mediate miR-665 packaging into cancer-cell-derived exosomes." (PMID 34349799, 2021). "Similarly, in this study, hnRNPA1 was up-regulated in A2780cisR cell line as compared to the level found in A2780 cells when A2780 was used as a reference, indicating that hnRNPA1 can be useful cancer biomarker and therapeutic target." (PMID 33053689, 2020). "Considering that hnRNPA1 can perform the variable splicing of PKM mRNA in order to increase the ratio of PKM2/PKM1 to promote cancer, the interaction with hnRNPA1 to splice the mRNA of PKM may be an important mechanism of SNHG6 that is involved in the metabolic process of CRC." (PMID 32296635, 2020). "In addition to the splicing-dependent function that may explain cancer-related phenotypes and other age-related diseases, the splicing-independent function of HNRNPA1 is also important for a well-understood regulatory mechanism." (PMID 31257225, 2019). "Therefore, the role of HNRNPA1 in cancers has been thoroughly studied." (PMID 31257225, 2019). "A variety of genes essentially modulate the expression level of hnRNPA1, affecting PKM2 expression and controlling the proliferation, apoptosis, and migration of cancer cells." (PMID 38785973, 2024). "Collectively, these findings suggest that ZMYND11 interacts with HNRNPA1 via the MYND domain and can limit the cytoplasmic translocation of HNRNPA1 to stress granules in stressed cells, thereby increasing the apoptosis of cancer cells." (PMID 39341825, 2024). "Our findings clearly indicate that ZMYND11 plays a critical role in inhibiting HNRNPA1-mediated oncogenic activities, including PKM splicing and stress granule formation, both of which are crucial for cancer cell survival and proliferation." (PMID 39341825, 2024). "The acetylated and phosphorylated hnRNPA1 increases its affinity with PKM pre-mRNA promoting PKM2 isoform generation and enhances cancer cell proliferation and invasion." (PMID 38785973, 2024). "We identify SLFN11, ETV4, HNRNPA1, and CMTM7 as promising markers of drug sensitivity in a number of common cancers." (PMID 39494610, 2024). "Mechanistically, SNHG6 induces hnRNPA1 to bind and splice PKM transcript in CRC cells, hence, sensitizing cancer cells for aerobic glycolysis sensitizing cancer cells for aerobic glycolysis." (PMID 37735423, 2023).